TNC (tenascin C)
Diseases named in the same sentence as TNC in open-access papers (continued):
Sharing a sentence is not in itself a finding about the gene and the disease.
asthma (continued). "In patients with asthma there was strong expression of both tenascin-C and MMP-1 in the sub-epithelial basement membrane and smooth muscle bundles." (PMID 24587395, 2014). "Asthma leads to structural changes in the airways, including the modification of extracellular matrix proteins such as tenascin-C." (PMID 21205293, 2011). "We have previously demonstrated that human patients with asthma show elevated levels of tenascin-C in the BM of the bronchi quite early after diagnosis." (PMID 21205293, 2011). "In human adult bronchi, tenascin-C expression is markedly higher in asthma patients in a stable phase and even immediately after specific antigen challenge." (PMID 21205293, 2011). "We show that IL-5 stimulation enhances extracellular matrix deposition, upregulates fibrotic mediators including collagen I, Fibronectin and Tenascin C, and promotes fibroblast cells survival, contributing to the persistent structural changes observed in asthma." (PMID 41188935, 2025). "Tenascin-C is present in high quantities in the airways of people with asthma." (PMID 40659888, 2025). "TNC expression is increased in a variety of cell types, including structural (fibroblast, airway smooth muscle, and endothelium) and immune (T and NK) cells in patients with asthma compared to healthy controls." (PMID 36829478, 2023). "TNC expression in the airway subepithelial reticular basement membrane in patients with asthma is prominently increased after allergen challenge and is a histopathological subepithelial marker to detect disease activity in asthma." (PMID 36829478, 2023). "The underlying key genes in asthma pathogenesis and those regulated by treatment including Adipoq, HMOX1, SPP1, Cyp2e1, TNC, MB, MPO, Col9a1, Ckmt2, and Erbb4 were taken as examples to illustrate the positions and relationships with other points and midline in the figure." (PMID 33531915, 2021). "The epithelial release of fibrogenic mediators such as TGF-β1/2, ET-, and TSP also has a distinct role in driving mesenchymal cell proliferation and ECM production (collagen I, III, HA, and tenascin-C) that are important features of airway remodeling in asthma." (PMID 32679790, 2020). "In a study using airway smooth muscle (ASM) cells from asthma and control patients, stimulation with Tenascin-C induced greater MMP-1 expression by asthma patient ASM-derived cells, via JNK, p38, and ERK1/2 MAPKs signaling, and blocking β1 and β3 integrins decreased this response." (PMID 29988449, 2018). "MMP-1 and tenascin-C are co-localised in the smooth muscle bundles of patients with asthma where this interaction may contribute to enhanced airway contraction." (PMID 24587395, 2014). "No published studies have shown association between asthma severity and tenascin-C expression to our knowledge." (PMID 21205293, 2011). "The expression of tenascin-C is increased in the airway wall in asthma." (PMID 21205293, 2011). "Furthermore, we examined the expression of Th1 (IFN-γ) cytokines, Th2 (IL-4) cytokines and TNF-α, which are all important in asthma and are possible regulators of tenascin-C expression." (PMID 21205293, 2011). "The accumulation of tenascin-C is associated with atopic but not with nonatopic asthma, and the thickness of the tenascin-C layer correlates with inflammatory cells in the lamina propria in atopic asthma." (PMID 21205293, 2011). "Tenascin-c (TNC) is an extracellular matrix glycoprotein that promotes tissue fibrosis in many disease models, including liver, lung, MS, and systemic sclerosis, and has strong associations with other inflammatory diseases, including cancer, asthma, and Alzheimer’s disease." (PMID 34772945, 2021). "However, although frequently being used as an additional tenogenic differentiation marker, tenascin-C is expressed in a wide variety of cell types and its upregulation is also associated with non-musculoskeletal diseases such as asthma or cancer." (PMID 25412928, 2014).
asthma (continued). "However, very little is known about the regulation of tenascin-C or its role in asthma in vivo." (PMID 21205293, 2011). "Other studies showed that the gene and/or protein expression of collagen I, fibronectin, versican, elastin, tenascin C, periostin, and vimentin was increased in ASMC and PF in asthma studies, including in vivo, ex vivo, in vitro, and animal model studies." (PMID 35456903, 2022). "TNC is considered an important gene in asthma pathogenesis and known as an extracellular matrix (ECM) protein whose expression is increased in asthma." (PMID 33531915, 2021). "Asthma derived ASM had higher basal expression of MMP-1 and higher tenascin-C stimulated MMP-1 levels than control ASM cells." (PMID 24587395, 2014). "Of functional relevance to asthma, MMP-1, collagen-I and tenascin-C are co-located in the airways of patients with asthma and ASM derived MMP-1 facilitated the agonist induced ASM contraction in vitro." (PMID 24587395, 2014). "Asthma derived ASM invitro had higher basal expression levels of MMP-1 and upregulated MMP-1 expression in response to tenascin-C via a β3-integrin sensitive mechanism in common with normal cells." (PMID 24587395, 2014). "To determine if tenascin-C regulates MMP-1 in disease, we examined the expression of tenascin-C and MMP-1 in the airways from five control donors and seven patients with asthma." (PMID 24587395, 2014). "Thickening of the reticular layer in asthma has been termed subepithelial fibrosis, and is due to deposition of fibrillar collagens (types I, III, and V), tenascin C, and fibronectin." (PMID 18348727, 2008). "Functionally, TNC promotes cell proliferation, migration, and integrin/PDGFR complex signaling in SM cells, and its expression is elevated in the airways and lavage fluid of patients with severe or refractory asthma." (PMID 41279414, 2025). "Study in TNC knockout (KO) mice showed that lung disease phenotype was largely attenuated in the absence of TNC in OVA-induced asthma." (PMID 33531915, 2021). "In patients with both mild and fatal asthma there is both an increase in constitutively expressed ECM proteins and re-expression of proteins normally restricted to the developing lung including tenascin-C and some laminin isoforms." (PMID 24587395, 2014). "Furthermore, TNC has also been shown to activate MAPK signalling through β1 and β3 integrins, which in turn upregulates matrix metalloproteinase-1 and mediates airway remodelling in asthma." (PMID 36829478, 2023). "TNC is highly expressed in many chronic lung diseases like chronic obstructive pulmonary disease (COPD), bronchopulmonary dysplasia (BPD), idiopathic pulmonary fibrosis (IPF), respiratory distress syndrome (RDS) and asthma, where it is even considered as a marker of severity." (PMID 32198404, 2020). "Silencing of TNC expression might be an interesting approach for the prevention of ASM thickening in patients with functional and structural airway obstruction or ventilation heterogeneity, like in asthma or COPD." (PMID 32198404, 2020). "Although we show that unstimulated asthma derived cells have similar tenascin-C gene expression to normal ASM, the Th2 cytokine IL-13, can strongly induce tenascin-C expression by ASM suggesting the asthma phenotype may induce ASM to synthesise tenascin-C." (PMID 24587395, 2014). "Tenascin-C and MMP-1 were not expressed in normal airways but co-localised in the ASM bundles and reticular basement membrane of patients with asthma." (PMID 24587395, 2014). "Little or no expression of TNC is found in normal adult lung; however, prominent Tnc expression has been reported in animal models of acute lung injury, in human idiopathic pulmonary fibrosis, COPD, and asthma." (PMID 25710175, 2015).
asthma (continued). "The absence of tenascin-C in control tissue, deposition in asthma and proximity to MMP-1 expression denote tenascin-C as a potential, pathologically-relevant, regulator of MMP-1 expression in vivo and target for therapeutic intervention against airway remodelling." (PMID 24587395, 2014).
pancreatic cancer (32 papers, 2008 to 2025). "In pancreatic cancer, the co-expression of the long isoform of TNC with membrane-associated annexin A2 (ANXA2) and the co-expression of TNC with MMP9 are significant indicators of poor patient prognosis." (PMID 40046232, 2025). "It has been reported that TNC is overexpressed in pancreatic cancer invasive fronts and is clinically associated with metastasis and poor prognosis." (PMID 29088796, 2017). "It has been reported that coexpression of MMP9 and TNC is significantly associated with pancreatic cancer metastasis." (PMID 29088796, 2017). "Tenascin-C (TNC), a large extracellular matrix glycoprotein, has been reported to be associated with metastasis and poor prognosis in pancreatic cancer." (PMID 29088796, 2017). "Tenascin C is a stromal marker previously reported to be induced in pancreatic cancer and has been implicated in metastasis in other cancer models." (PMID 26077591, 2015). "In pancreatic cancer, however, TNC is primarily expressed by CAFs and engages integrin receptors on tumor cells to promote EMT, enhance invasiveness, and confer drug resistance." (PMID 41174721, 2025). "The levels of POSTN and TNC increase in tumors such as breast, lung, and pancreas carcinomas, where they interact with other ECM molecules to promote cancer cell survival, invasion, and metastatic spreading." (PMID 39201614, 2024). "In pancreatic cancer, stromal pancreatic stellate cells secreted Wnt and tenascin C (TnC) ligand molecules promoting the β-catenin and YAP/TAZ signaling pathways." (PMID 36550571, 2022). "MET-dependent tenascin C modulation in pancreatic cancer cells was validated at RNA and protein levels both in vitro and in vivo." (PMID 34298732, 2021). "High TNC expression, and downstream signaling through the Annexin II receptor, have been initially correlated with poor prognosis but this association is still controversial and could depend on the stage and grade of the pancreatic tumor or the specific location of TNC." (PMID 33889150, 2021). "Increased TNC expression was observed in tumors after radiation exposure in a pancreatic cancer mouse model." (PMID 33291427, 2020). "Overexpressed ECM molecules, including thrombospondin, periostin, hyaluronic acid (HA), tenascin-C, vitronectin, collagens, and fibronectin increase pancreatic cancer cell migration and invasion." (PMID 32481570, 2020). "Various studies reported that TNC has a significant link to breast, lung, colon, gastric and pancreatic cancer progression with metastatic phenotype." (PMID 31798767, 2019). "It was shown that TNC markedly increased the expression of p-PaxillinS178 Paxillin-dependent manner, which indicated that TNC modulates the phosphorylation of PaxillinS178 in pancreatic cancer cells." (PMID 29088796, 2017). "The data indicated that the JNK signalling pathway mediated TNC-regulated aggressive behaviour in pancreatic cancer cells." (PMID 29088796, 2017). "In this study, our data provides evidence that TNC leads to increased phosphorylation of JNK/c-Jun in pancreatic cancer cells." (PMID 29088796, 2017). "While in normal pancreas tissue only a low molecular weight isoform of TNC was detectable, pancreas tumor tissues expressed additional higher molecular weight isoforms." (PMID 22947174, 2012). "Pancreatic cancer (PDAC) is characterized by an abundant fibrous tissue rich in Tenascin-C (TNC), a large ECM glycoprotein mainly synthesized by pancreatic stellate cells (PSCs)." (PMID 21747918, 2011). "In this study, we performed an extensive analysis of the effects of exogenous TNC on pancreatic cancer cell functions and we investigated the effect of endogenous TNC overexpression in the pancreatic cancer cell line PANC-1." (PMID 21747918, 2011). "Moreover, because TNC can activate JNK, it can enhance the association of paxillin with FAK, which promotes pancreatic cancer cell motility and adhesion." (PMID 35409206, 2022).
pancreatic cancer (continued). "However, overexpression of tenascin-C together with other ECM-related factors has been shown to correlate with poor prognosis for patients of pancreatic cancer." (PMID 32481570, 2020). "However, it was found to be highly expressed in pancreatic cancer, and expression of TNC is correlated with cancer metastasis and the progression from low-grade precursor lesions to PDAC." (PMID 29088796, 2017). "Thus, we observed that TNC functions in the regulation of the expression and activity of type IV collagenases in pancreatic cancer cells." (PMID 29088796, 2017). "To investigate whether TNC regulates migration and invasion in pancreatic cancer cells, we first knocked down the expression of TNC in Capan-2, AsPC-1 and PANC-1 cells using siRNA targeting human TNC mRNA." (PMID 29088796, 2017). "In addition, clinical evidence has shown that co-expression of MMP9 and TNC contributes to pancreatic cancer progression." (PMID 29088796, 2017). "However, ectopic expression of TNC in pancreatic cancer cells resulted in downregulation of E-cadherin and upregulation of N-cadherin and Vimentin, as evidenced by western blot analysis and immunofluorescence assay." (PMID 29088796, 2017). "TNC affects proliferation, migration and adhesion of poorly differentiated pancreatic cancer cell lines and might therefore play a role in PDAC spreading and metastasis in vivo." (PMID 21747918, 2011). "Endogenous TNC promoted pancreatic cancer cell growth and migration." (PMID 21747918, 2011). "However, low levels of TNC mRNA were found in pancreatic cancer cell lines by real-time quantitative PCR." (PMID 21747918, 2011). "TNC may be a potential therapeutic target for treating pancreatic cancer metastasis." (PMID 29088796, 2017). "Thus, TNC might act as a potential therapeutic target and predictor for pancreatic cancer metastasis at an early stage." (PMID 29088796, 2017). "Furthermore, the nude mouse intraperitoneal tumor metastasis experiments showed that injection of PANC-1 cells with TNC overexpression induced the numbers of abdominal metastasis nodules These data indicate that TNC is essential in pancreatic cancer development and metastasis." (PMID 29088796, 2017). "In conclusion, this work identifies tenascin C as a gene modulated by MET activation, suggesting a role in MET-mediated tumor-stroma interplay occurring during pancreatic tumor progression." (PMID 34298732, 2021). "In this study, we indicated that overexpression of TNC has a significant effect on inducing EMT via increased phosphorylation of JNK and c-Jun in pancreatic cancer." (PMID 29088796, 2017). "In pancreatic cancer, ectopic tenascin C expression in RIP-Taq2 mice significantly increased the establishment of micrometastases, whereas a tenascin C knockout reduced tumor cell engraftment in the lungs." (PMID 26539408, 2015). "Up-regulation of TNC in cancer progression seems to involve specifically the large splice variant, as the largest TNC transcript, corresponding to the unspliced form of TNC, is found in pancreatic cancer and in chronic pancreatitis, but not in the normal pancreas." (PMID 21747918, 2011). "Our results point to a main role of TNC in the regulation of the interactions between epithelial cells and ECM in the progression of pancreatic cancer." (PMID 21747918, 2011). "It has been observed that tenascin-C (TNC), an extracellular matrix glycoprotein, may influence metastases and contribute to the poor prognosis of patients with pancreatic cancer." (PMID 35409206, 2022). "Our results highlight a new role for tenascin C, which could represent the operative arm through which MET promotes activation of the stromal compartment in pancreatic cancer." (PMID 34298732, 2021).
pancreatic cancer (continued). "One of them, Tenascin-C expression is upregulated and has been involved in gastric and gastric GIST cancer progression, increased proliferation in pancreatic cancer and is a prognostic determinant of colorectal cancer through induction of epithelial to mesenchymal transition and proliferation." (PMID 31027181, 2019). "We speculated that TNC might regulate MMP9 expression and thus be involved in metastatic processes in pancreatic cancer, but we found that the expression of TNC did not affect MMP2 expression in these cells." (PMID 29088796, 2017). "We found that ectopic expression of TNC in pancreatic cancer cells resulted in downregulation of the epithelial marker E-cadherin and concomitant downregulation of the mesenchymal markers N-cadherin and Vimentin, whereas SP600125 significantly reversed the TNC-induced change in EMT markers." (PMID 29088796, 2017).